IL25 (interleukin 25)
Diseases named in the same sentence as IL25 in open-access papers (continued):
Sharing a sentence is not in itself a finding about the gene and the disease.
nasal polyps (25 papers, 2009 to 2025). "Notably, increased IL‐25 production in nasal polyps is associated with corticosteroid sensitivity." (PMID 34617355, 2021). "Aeroallergens induce DCLK1+IL-25+ tracheal tuft cell expansion in mice and DCLK1+ tuft cells produce IL-25 in patients with chronic rhinosinusitis with nasal polyps." (PMID 38061015, 2024). "Tracheal tuft cells are a primary source of IL-25 in mice, and tuft cells produce IL-25 in human patients with chronic rhinosinusitis with nasal polyps." (PMID 38061015, 2024). "Elevated levels of IL-25 in nasal polyps are also indicative of a positive response to corticosteroid treatment." (PMID 38680486, 2024). "After exposure to allergens, IL-25 is markedly upregulated in the bronchial mucosa and nasal polyps of CRSwNP patients." (PMID 38680486, 2024). "Increased IL-25 expression in nasal polyps compared to control and CRSsNP was reported in CRS patients from Asian countries such as China, Japan and Korea, while no significant upregulation was reported in CRS patients from the United States and Australia." (PMID 35387020, 2021). "Interleukin (IL)-10, IL-25, IL-33, and thymic stromal lymphopoietin (TSLP) levels were determined using the enzyme-linked immunosorbent assay (ELISA) in nasal polyp tissues." (PMID 32294933, 2020). "Chemosensory cells of the nasal epithelium are the source of IL-25 and are increased in the inflamed nasal epithelium of patients with nasal polyposis." (PMID 33332460, 2020). "This study aimed to measure the expressions of IL-17RB, ST2 and TSLPR, receptor of IL-25, IL-33, and TSLP respectively, on myeloid DCs in nasal polyps (NP) and evaluate their association with local Th2 inflammation and disease severity in patients with NP." (PMID 30519393, 2018). "in NPDFs and increased expression of IL-25 were also involved in the pathogenesis of nasal polyposis by affecting nasal fibroblasts in chronic rhinosinusitis with nasal polyps." (PMID 28771607, 2017). "Our results indicate that IL-25, one of the dominant cytokines in Asian nasal polyps, also induce the expression of α-SMA in NPDFs in a dose-dependent manner." (PMID 28771607, 2017). "We also evaluated the effects of IL-25 on the activations of fibroblasts, one of the main components of nasal polyps and a main determiner of tissue composition." (PMID 28771607, 2017). "Interleukin (IL)-25 has been shown to play an important role in the pathogenesis of chronic rhinosinusitis with nasal polyps." (PMID 28771607, 2017). "Cellular sources of IL-25 within nasal polyp tissue were investigated by using immunohistochemistry." (PMID 26684290, 2016). "Additionally, IL-25 exposure activates type 2 innate lymphoid cells and Th2 cells in nasal polyp cells, boosting Th2 cytokine production in vitro." (PMID 41303221, 2025). "Indeed, IL-25 is highly expressed in nasal polyp tissues, where this alarmin amplifies the activation of Th2 and ILC2 cells, thereby worsening both endoscopic nasal polyp score and computed tomography score." (PMID 34572294, 2021). "Double immunofluorescent staining (Vimentin/ α-SMA or IL-25/ α-SMA) was conducted to investigate whether myofibroblasts (active form of fibroblast) were involved in pathogenesis of nasal polyp of the CRSwNP group." (PMID 28771607, 2017). "Despite differing reports regarding the expression levels of TGF-β1 or patterns of connective tissue composition in CRSwNP, it is generally understood that the expression of IL-25 is significantly higher in the nasal polyps of CRSwNP patients than in CRSsNP patients or control subjects." (PMID 28771607, 2017). "Interleukin-25 (IL-25) induces myofibroblast differentiation, extracellular matrix production and matrix metalloprotease expression in nasal fibroblasts via the NF- κB signaling pathway, thus aiding the process of the tissue growth and leading to nasal polyposis in chronic rhinosinusitis." (PMID 34305932, 2021).
nasal polyps (continued). "The expression levels of IL-25 and TSLP are higher in nasal polyps of patients with ECRS than in normal nasal mucosa." (PMID 39015572, 2024). "In epithelial cells of nasal polyps (eosinophil-rich areas), TSLP, IL-25, and IL-33 were higher than in those of uncinate process tissues (eosinophil-poor areas)." (PMID 32085629, 2020). "In this manuscript we explore the reactivity of epithelial cells isolated from nasal polyps and healthy controls to a broad range of TLR agonists in their ability to induce the expression and production of TSLP, IL-25, and IL-33." (PMID 27050744, 2016). "The aim of this study is to evaluate the effects of IL-25 on myofibroblast differentiation, ECM production and the expression of matrix metalloproteinases in nasal polyp derived fibroblasts (NPDFs) and to determine the molecular mechanism underlying these processes." (PMID 28771607, 2017). "Our observation suggests that viral infections may enhance the T2 biased immunologic response of nasal polyps through the release of TSLP and IL-25 by epithelial cells." (PMID 28127565, 2016). "Our results suggest that IL-25-induced release of α-SMA, fibronectin, collagen, MMP-1 and MMP-13 from NPDFs is mediated by the combined activation of the MAPK and NF-kB pathways, thereby providing new clues for fibroblast-mediated inflammation by changing the ECM composition in nasal polyps." (PMID 28771607, 2017). "We report that epithelial cells derived from nasal polyps of patients with CRSwNP release TSLP and IL-25 when specifically stimulated by poly(I:C), while they could not be activated by the stimulation with Dermatophagoides pteronyssinus or Aspergillus fumigatus extracts." (PMID 28127565, 2016). "Moreover, we see only the increased TSLP induction and no increased induction of the other Th2-skewing mediators IL-25 and IL-33 in nasal polyposis epithelium." (PMID 27050744, 2016). "In none of the baseline or induced conditions of primary healthy epithelium or epithelium isolated from nasal polyps could we detect any IL-25 mRNA in our real time PCR set up, despite that our protocol was able to amplify IL-25 mRNA from a positive control (data not shown)." (PMID 27050744, 2016).
viral infection (25 papers, 2012 to 2025). "It is known that viral infections increase the expression of airway epithelium-born cytokines such as IL-25, IL-33, and thymic stromal lymphopoietin (TSLP) and stimulate ILC2 responses." (PMID 36326393, 2022). "Following the local epithelial damage due to viral infection, production of IL-25, IL-33, and TSLP increases, which stimulates ILC2s, and as a result, T2 inflammation is induced." (PMID 36326393, 2022). "In response to pathogen recognition, allergen exposure or viral infection, epithelial cell-derived cytokines such as IL-25 and IL-33 are released." (PMID 34220812, 2021). "ILC2s are potently activated by epithelial cell-derived IL-25 and IL-33, both of which are released in response to allergens, viral infection, and epithelial injury." (PMID 30654796, 2019). "Exacerbation studies involving OVA-induced inflammation and viral infection indicated that IL-25 is importantly involved." (PMID 26879906, 2016). "Blocking IL-25 is evidence to support innate immune-targeting approaches that re-calibrate mucosal innate immunity to improve the capacity for endogenous IFN production during viral infection." (PMID 35508632, 2022). "We hypothesized that IL-25 directly regulates BEC innate immunity during viral infection and inhibition of IL-25 (in addition to suppressing type 2 inflammation), increases IFN expression and reduces viral load." (PMID 35508632, 2022). "Indeed, viral infections may exacerbate Th2‐high inflammation by inducing epithelial cell‐derived cytokines such as IL‐25, IL‐33, and thymic stromal lymphopoietin (TSLP), which further activate and recruit type 2 helper T cells and eosinophils." (PMID 39466641, 2025). "However, the relationship between IL-25 and viral infections is largely unknown." (PMID 39261649, 2024). "Higher levels of inflammatory mediators like IL-25, IL-1β, IL-10, IL-5 and tumor necrosis factor (TNF) -α after viral infection were found in human nasal epithelial cell (HNEC) culture compared to controls." (PMID 38116043, 2023). "Viral infection disrupts the epithelial barrier, resulting in the thymic stromal lymphopoietin and pro-TH2 cytokines IL-25 and IL-33." (PMID 34831860, 2021). "In response to viral infections, such as RSV, IAV, or rhinovirus, lung-resident ILC2 are activated by tissue damage via the production or release of IL-25 or IL-336,18,33,46–48." (PMID 30770814, 2019). "IL-25 promoted the infection of HSV-1 among AD patients by suppressing the expression of interferon-gamma (IFN-γ), a key factor for the host to defend against viral infection." (PMID 36119076, 2022). "In conclusion, our data suggest that viral infection may contribute to maintaining and amplifying the T2 immune response commonly seen in CRSwNP, through the release of TSLP and IL-25 by epithelial cells of polyps." (PMID 28127565, 2016). "During bacterial and viral infections, local sensor cells in respiratory tract, including airway epithelia cells, alveolar macrophages and dendritic cells, firstly response to pathogens and secret the first-order cytokines, such as type I and III IFN, IL-6, TNF-α, IL-12, IL-25, IL-33, IL-1β, etc.." (PMID 38029253, 2023). "CRSwNP epithelial cells release TSLP and IL-25 when stimulated by poly(I:C) but not by DP or AF, suggesting that viral infection may contribute to maintain and amplify the T2 immune response seen in CRSwNP." (PMID 28127565, 2016).
pulmonary fibrosis (21 papers, 2014 to 2025). Chronic progressive interstitial lung disorder characterized by the replacement of the lung tissue by connective tissue, leading to progressive dyspnea, respiratory failure, or right heart failure. "In a preclinical mouse model, IL-25 (also known as IL-17E) activated innate lymphoid cells (ILC2s)-2 and caused pulmonary fibrosis." (PMID 35626756, 2022). "IL-25 is a Th2 cytokine regulator, and previous reports revealed an association between IL-25 and pulmonary disorders such as pulmonary fibrosis and airway remodeling." (PMID 28623940, 2017). "IL17B has been reported to have a proinflammatory activity similar to IL25 in lung fibrosis and eliciting type 2 cytokine responses." (PMID 36814913, 2023). "IL-25 was upregulated in the alveolar epithelial cells and lung fibroblasts of patients with idiopathic pulmonary fibrosis." (PMID 37005677, 2023). "The important roles and mechanisms of IL‐25/IL‐33/TSLP are mainly elucidated by experimental murine lung fibrosis model induced by BLM or S. mansoni eggs." (PMID 36082495, 2022). "Increased pulmonary expression of IL-25 is found in idiopathic pulmonary fibrosis, and a population of ILC2s is also observed in the lungs of idiopathic pulmonary fibrosis patients." (PMID 35008429, 2021). "It has been demonstrated recently, that the upregulated IL-25 axis contributes to lung fibrosis by promoting profibrotic phenotype changes of the alveolar epithelial cells and direct activation of fibroblasts." (PMID 31581688, 2019). "Recently, it was reported that IL-17B, which (like IL-25) is a ligand for IL-17RB, is crucial for development of bleomycin-induced pulmonary fibrosis in mice by promoting type 3 immune responses in mice." (PMID 31745167, 2019). "The role of ILC2s in pulmonary fibrosis and airway inflammation is supported in animal models where the production of IL-13 by IL-25-elicited ILC2s was sufficient to drive collagen deposition in the lungs of bleomycin-challenged mice." (PMID 31354734, 2019). "In the mouse model of pulmonary fibrosis that uses injection of S. mansoni eggs, IL-25 has been shown to be the key cytokine in the development of fibrosis." (PMID 28271447, 2017). "Despite the relations of the pulmonary fibrosis with IL-25, IL-33, and TSLP, the clinical implications of these cytokine remain poorly defined due to the small number of subjects (less than 15) examined in the previous studies." (PMID 28202030, 2017). "Group 3 ILCs promoted bleomycin-induced pulmonary fibrosis by secreting IL-17, whereas IL-25 induced expansion of the group 2 ILCs within the lungs, which promoted pulmonary fibrosis via IL-13 dependent mechanism." (PMID 27597803, 2016). "IL‐25 may promote lung fibrosis by activating IL‐17BR+fibroblast and IL‐17BR+ILC2 (type 2 innate lymphoid cell)." (PMID 36082495, 2022). "IL‐25 promotes lung fibrosis in a IL‐13+IL‐17BR+ILC2 dependent fashion." (PMID 36082495, 2022). "Likewise, intranasal delivery of recombinant IL-25 to mice caused airway inflammation, connective tissue growth factor (CTGF) and TGF-β1 production and subsequent pulmonary fibrosis." (PMID 31354734, 2019). "Innate T helper type 2 (Th2) immune responses mediated by interleukin (IL)-33, thymic stromal lymphopoietin (TSLP), and IL-25 have been shown to play an important role in pulmonary fibrosis of animal models; however, their clinical implications remain poorly understood." (PMID 28202030, 2017). "Pulmonary expression of IL-25 has been shown to be increased in patients with IPF, and is essential in the generation of experimental pulmonary fibrosis: IL-25 levels were shown to be higher in the BAL fluid of patients with IPF compared with a small number of controls." (PMID 28202030, 2017).
pulmonary fibrosis (continued). "We have done a literature search using the following terms: (“idiopathic pulmonary fibrosis” OR “IPF” OR “lung fibrosis”) and (TSLP or “thymic stromal lymphopoietin” or IL‐25 OR IL‐17E OR IL‐33) from the database of PubMed published in English up to July 2018." (PMID 36082495, 2022). "It has been well elucidated that IL‐25/IL‐33/TSLP plays an important role in allergic airway inflammation and remodeling, whereas their roles in idiopathic pulmonary fibrosis (IPF) still remained largely unclear." (PMID 36082495, 2022). "Recently studies employing animal models proved that IL-25, IL-33, and TSLP have an emergent role in the generation of pulmonary fibrosis." (PMID 31581688, 2019). "In humans, increased levels of IL-25 and ILC2s are found in the BAL and lung tissue of patients with idiopathic pulmonary fibrosis." (PMID 28271447, 2017). "In this context, an interplay between ILC, macrophages, and cells of the adaptive immune system was shown to participate—together with IL-13, IL-25, and IL-33—in the pathogenesis of BLM-induced pulmonary fibrosis in mice." (PMID 28018357, 2016). "IL‐25/IL‐33/TSLP and their corresponding receptors, that is, IL‐17BR/ST2L/TSLPR, are shown to be up‐regulated both in IPF patients and bleomycin (BLM)‐induced lung fibrosis mice model." (PMID 36082495, 2022). "Similarly to IL-25 or TSLP, IL-33 can be found in increased concentrations in the BAL and lung tissue of IPF patients and is upregulated in experimental lung fibrosis." (PMID 34093523, 2021). "Similarly, it has recently been shown that IL-25 is upregulated in IPF lung tissue samples and promotes lung fibrosis by directly mediating alveolar epithelial cells and fibroblast activation." (PMID 31581688, 2019). "IL-25 can also promote the infiltration of eosinophils and CD4+ T cells into the airways and skin by promoting a type 2 cytokine response, which may even induce pulmonary fibrosis during allergic inflammation." (PMID 37005677, 2023). "As far as we know, no previous studies reported that IL-25 and TSLP pathways leading to lung fibrosis might be impacted by pirfenidone." (PMID 31581688, 2019).
airway hyperresponsiveness (18 papers, 2015 to 2025). "RV infection of 6 day-old mice, but not mature mice, induces type airway inflammation, mucous metaplasia and airways hyperresponsiveness which is associated with expansion of IL-13-producing ILC2s and dependent on the innate cytokines IL-25, IL-33 and TSLP." (PMID 41573550, 2025). "Specifically, among epithelium-associated cytokines, IL-25 exacerbates allergic inflammation by epithelial cell hyperplasia, mucus secretion, airway hyperresponsiveness, and production of specific Th2 cytokines." (PMID 28912627, 2017). "iNKT cells that migrate to the lung tissue are known to cause IL-25-dependent airway hyperresponsiveness (AHR)." (PMID 26482437, 2015). "RV infection of 6 day-old mice, but not mature mice, induces type 2 airway inflammation, mucous metaplasia and airways hyperresponsiveness which is associated with expansion of IL-13-producing type 2 innate lymphoid cells (ILC2s) and dependent on the innate cytokines IL-25, IL-33 and TSLP." (PMID 41573550, 2025). "We have shown that RV1B infection of 6-day-old mice induces mucous metaplasia and airway hyperresponsiveness that is associated with ILC2 expansion and dependent on IL-13, IL-25, IL-33, and TSLP." (PMID 38061015, 2024). "We found that exogenous IL-25 indeed decreased airway neutrophilia and airway hyperresponsiveness in the mouse model." (PMID 37898756, 2023). "On the contrary, the combined blockade of type 2 cytokines, namely, IL-13 and IL-25, was more effective than the obstruction of either cytokine in reducing the infiltration of inflammatory cells in the airways with attenuated airway hyperresponsiveness and tissue remodeling." (PMID 36834723, 2023). "Notably, combined blockade of type 2 cytokine IL-13 and IL-25 was even more effective than blockade alone in reducing infiltration of inflammatory cells in the airways with attenuated airway hyperresponsiveness and tissue remodeling." (PMID 34122457, 2021). "Then airway hyperresponsiveness (AHR), eosinophil percentage, levels of interleukin (IL)‐33, IL‐25, IL‐13, IL‐5, IL‐4, total and ovalbumin (OVA)‐specific immunoglobulin (Ig)E, and lung histopathology were evaluated." (PMID 38664220, 2024). "Additionally, asthmatic patients with higher levels of IL-25 messenger RNA levels had greater airway hyperresponsiveness to allergens, increased serum IgE, airway and blood eosinophils levels and more beneficial responses to inhaled corticosteroids compared asthmatics with low IL-25 expression." (PMID 30386455, 2018). "We have shown that rhinovirus A1B (RV1B) infection of 6-day-old mice, but not mature mice, induces mucous metaplasia and airway hyperresponsiveness that is associated with ILC2 expansion and dependent on IL-13, IL-25, IL-33, and TSLP." (PMID 38061015, 2024).